PPARG (peroxisome proliferator activated receptor gamma)
Diseases named in the same sentence as PPARG in open-access papers (continued):
Sharing a sentence is not in itself a finding about the gene and the disease.
metabolic syndrome (335 papers, 2004 to 2026). A cluster of metabolic risk factors for CARDIOVASCULAR DISEASES and TYPE 2 DIABETES MELLITUS. "Deficiencies in PPARγ and leptin are associated with metabolic syndrome, characterized by dyslipidemia, renal hypertrophy, and elevated levels of the profibrotic cytokine transforming growth factor beta (TGFβ) in the kidneys." (PMID 40149950, 2025). "Previous research has reported that a PPARG Pro12Ala polymorphism was associated with dyslipidemia and cardiovascular disease because PPAR-γ regulates the expression of key proteins involved in lipid metabolism." (PMID 37376225, 2023). "Our recent study in a rat model observed that hepatic dyslipidemia/adipogenesis caused by olanzapine was correlated with histone modulation of the PPARγ pathway and lipid storage." (PMID 37298094, 2023). "To figure out the potential associations between BCAA and the anti-dyslipidemia effect of CO, we further performed the relative expression of the PPARγ gene in the liver of mice." (PMID 35745155, 2022). "At present, there is contradictory data on the association of PPARG rs1801282 with the development of metabolic syndrome (MS) and T2D." (PMID 35292917, 2022). "Peroxisome proliferator-activated receptor gamma (PPARγ) is implicated in several metabolic syndromes, including DN." (PMID 32774472, 2020). "Peroxisome proliferator-activated receptor-γ (PPARγ) is a master regulator of adipogenesis, and alterations in its function are associated with various pathological processes related to metabolic syndrome." (PMID 30618832, 2018). "Within the last two decades, PPARγ became a focus of attention as a transcription factor implicated in metabolic syndrome." (PMID 27483259, 2016). "Postprandial hypertriglyceridemia is associated with lower PPARG expression in metabolic syndrome patients while in healthy subjects the same “insult” leads to overexpression of PPARG." (PMID 27579030, 2016). "PPARγ has been implicated in almost all features of metabolic syndrome, including obesity, hypertension, dyslipidemia, insulin resistance, and inflammation." (PMID 26712739, 2015). "The nuclear receptor PPARγ is a key regulator of adipogenesis, and alterations of its function are associated with different pathological processes related to metabolic syndrome." (PMID 24790595, 2014). "In HFD-fed mice, the increased methylation of the PPARγ promoter accompanied by the decreased expression of PPARγ mRNA in visceral adipose tissues was associated with the pathogenesis of metabolic syndrome." (PMID 24905748, 2014). "Results of logistic regression model demonstrated the main effect of circulating PPARγ on the risk of metabolic syndrome and its components." (PMID 24330836, 2013). "Research demonstrated PPARγ agonists would increase the circulating adiponectin in a metabolic syndrome rat model, and an epidemiological study proved that PPARγ gene polymorphism would affect the serum adiponectin levels." (PMID 23342006, 2013). "We found the 1.901 increased risk of metabolic syndrome in subjects with higher concentration of PPARγ in compared with lower concentration of PPARγ after adjustment for age, sex and BMI (pvalue = 0.037, 95% CI from 1.041 to 3.473)." (PMID 24330836, 2013). "We aimed to assess the possible influence of circulating PPARγ on relative risk of metabolic syndrome and also examine the association between circulating PPARγ and adipokines levels among obese subjects." (PMID 24330836, 2013). "The risk of metabolic syndrome in subjects with higher concentration of PPARγ was higher in compared with lower concentration of PPARγ after adjustment for age, sex and BMI." (PMID 24330836, 2013). "The risk of metabolic syndrome in subjects with higher concentration of PPARγ was 1.9 fold in compared with lower concentration of PPARγ after adjustment for age, sex and BMI." (PMID 24330836, 2013). "Further, PPARγ is also implicated in the modulation of metabolic syndrome that causes cardiovascular complications." (PMID 20828387, 2010).
metabolic syndrome (continued). "PPARγ has been implicated in almost all aspects of the cluster of human diseases designated as metabolic syndrome." (PMID 20148112, 2010). "Therefore, patients with EOD and metabolic syndrome should be screened for PPARγ variants, even if they lack typical lipodystrophy features." (PMID 34764936, 2021). "Lower expression of PPARγ is linked to the pathogenesis of metabolic syndrome, whereas increased OXPHOS have been associated to increased basal respiration and oxidative stress a characteristic of adipocytes from insulin resistant obese-nondiabetic humans and mice." (PMID 33924880, 2021). "In this study, we verified the hypothesis that the metabolic stress sensor TRIB3 collaborates with the oncoprotein PML-RARα to inhibit PPARγ activity and subsequently cause dyslipidemia in newly diagnosed APL patients." (PMID 32929351, 2020). "Understanding more about PPARG activity in the adipogenic process is directly linked to its possible contribution to the onset and progression of metabolism-related pathologies, including the metabolic syndrome and its complications." (PMID 24790595, 2014). "Accordingly, we design current study to assess the possible influence of circulating PPARγ on relative risk of metabolic syndrome and also examine the association between various levels of PPARγ and different pattern of circulating adipokines among obese subjects." (PMID 24330836, 2013). "Importantly, a frequent coding SNP in the PPARγ gene, the Pro12Ala variant, has consistently been associated in metabolic studies with BMI, insulin sensitivity, the metabolic syndrome." (PMID 23431284, 2013). "If the absence of estrogen leads to abdominal fat deposition, it is possible that reduced PPARG expression may act cooperatively to potentiate metabolic syndrome-related symptoms that are often associated with increased waist girth." (PMID 21062459, 2010). "Although the details of the regulatory mechanisms controlling the activity and the amount of PPARγ at the various levels remains unclear, these alterations appear to be strongly associated with the pathogenesis of metabolic syndrome." (PMID 19589179, 2009). "Therefore, any reduction in amount and activity of PPARγ is linked to the pathogenesis of metabolic syndrome." (PMID 19589179, 2009). "On the other hand, trans and saturated fatty acids not only reduce PPARγ expression but are also associated with increased inflammation and impaired lipid metabolism, which can raise the risk of metabolic diseases such as nonalcoholic fatty liver disease and metabolic syndrome." (PMID 40968591, 2025). "Thus, galectin-12, resistin, leptin, and other adipokines/cytokines regulated by PPARγ may act synergistically to affect lipid metabolism in metabolic tissues, contributing to the dyslipidemia associated with APL." (PMID 32929351, 2020). "Thus, the expression and epigenetic regulation of PPARγ mRNA might also be important for the maintenance of the adipocyte phenotype, and any defect in this regulation could become a pathogenic factor in metabolic syndromes." (PMID 19589179, 2009). "PPARγ gene therapy targets PPARγ to improve insulin sensitivity and lipid metabolism in individuals with metabolic syndrome, offering a potential cure for disorders stemming from PPARγ dysfunction." (PMID 40926269, 2025). "This upregulation of PPARγ was caused by the AdipoR1/AMPK signaling pathway, which plays a pivotal role in improving dyslipidemia." (PMID 40332475, 2025). "This complements strategies in other studies where PPARG agonists have been used to treat metabolic syndrome, but this study further expands the potential value of PPARG agonists in anti-inflammatory and immune modulation aspects." (PMID 40565585, 2025). "Enhanced expression of PPARγ likely drives improved adipocyte differentiation, fatty acid oxidation, and insulin signaling in adipose and liver tissues, thereby attenuating dyslipidemia and hyperglycemia; these effects are amplified in the combined group." (PMID 41407819, 2025).
metabolic syndrome (continued). "Caffeic acid phenethyl ester (CAPE) has been reported to improve metabolic syndrome, inhibit basal lipolysis and activate adipose tissue remodeling via the PPARγ signaling pathway in high-fat diet-induced obese rats." (PMID 39458839, 2024). "GLUT8 deficiency prevents fructose-induced fat accumulation, glycemic dysregulation, and dyslipidemia through PPARγ and its downstream targets." (PMID 38397903, 2024). "This suggests that DNA methylation of the nuclear receptors PPARγ and PPARα is correlated with metabolic deregulation, the pathogenesis of metabolic syndrome, and the induction of inflammation." (PMID 39062500, 2024). "Overall, these results pave the way for potential treatment targeting MP PPARγ signaling in dyslipidemia-mediated inflammation, such as DR, and potentially beyond retinal vasodegeneration." (PMID 37781924, 2023). "This study provides comprehensive insights into the glycemia-independent activation of Mos in T2DM and identifies MP PPARγ as a target for dyslipidemia-activated MPs in DR." (PMID 37781924, 2023). "peplus is rich in flavonoids, and its extract ameliorated IR, hyperglycemia, dyslipidemia, inflammation and redox imbalance, and upregulated adiponectin and PPARγ in rats with T2D." (PMID 37397470, 2023). "Focusing on PPARγ, an insulin-sensitizing protein involved in the inhibition of lipogenesis, it makes sense that in our study, PPARγ levels were lower in SAT of metabolic syndrome and dyslipidaemic patients compared to that in healthy subjects." (PMID 36077270, 2022). "Several studies have linked these two common PPARγ polymorphisms to a lowered risk of CAD (coronary artery disease) and metabolic syndrome in different groups and the conclusions have been disputed." (PMID 36292779, 2022). "We herein reveal five novel high-resolution structures of PPARδ/γ–bezafibrate, PPARγ–fenofibric acid, and PPARδ/γ–pemafibrate, thereby providing the molecular basis for their application beyond dyslipidemia treatment." (PMID 35563117, 2022). "It has been reported that PPARγ has a key role in the low-grade inflammation and adipogenesis in metabolic syndrome." (PMID 34679777, 2021). "Pioglitazone a PPARγ agonist, decreased IR in major metabolic tissues, dyslipidemia, and the hepatic lipid accumulation in iNOS-/- mice as suggested by decreased liver/body weight ratio." (PMID 35008623, 2021). "To efficiently evaluate the ligands for PPARγ, a target molecule for metabolic syndrome and inflammatory diseases, we synthesized compound 2 using our method." (PMID 33919837, 2021). "Peroxisome proliferator-activated receptor γ (PPARγ) is a molecular target of metabolic syndrome and inflammatory disease." (PMID 33919837, 2021). "Here, we identified that APL cells with defective PPARγ function is likely the essential factor triggering the dyslipidemia of APL patients by secreting resistin and subsequently disrupting the lipid metabolism of hepatocytes." (PMID 32929351, 2020). "Using PPARγ (peroxisome proliferator-activated receptor) agonists for the treatment of metabolic syndrome, which is a multifaceted health problem, is a striking example of the applicability of multi-target drugs." (PMID 33096688, 2020). "Although arsenic/ATRA therapy degraded PML-RARα and restored PPARγ expression, it exacerbated dyslipidemia in APL patients." (PMID 32929351, 2020). "In summary, our study not only reveals a critical role of the PML-RARα/PPARγ/TRIB3 axis in dyslipidemia for patients with APL but also confers a rationale for the combination of ATRA/arsenic with the PPAR activator for the treatment of patients with APL." (PMID 32929351, 2020). "The advantages of PPARα and PPARγ agonists in the treatment of metabolic syndrome have led to the development of PPARα/γ dual agonists." (PMID 30733541, 2019). "Fibrates (PPARα agonists) and TZDs (PPARγ agonists) remain two of the mainstream therapeutic agents for dyslipidemia, T2DM, and CVD prevention." (PMID 31614690, 2019).
metabolic syndrome (continued). "Since the lipid-lowering activity of PPARα agonists and insulin-sensitizing effect of PPARγ agonists are extremely well-established and have been widely exploited to improve dyslipidemia and T2DM, these aspects will be excluded from this review." (PMID 31614690, 2019). "Hypermethylation of FTO, hypermethylation of PPARγ, and hypomethylation PDK4 associated with metabolic syndrome, T2D and both metabolic syndrome and T2D, respectively." (PMID 30564199, 2018). "The partial agonist activity of idebenone on both PPARα and PPARγ, combined with its excellent safety profile in humans, suggested a potential role in the treatment of metabolic syndrome diseases." (PMID 30171034, 2018). "In this study, we found that COS improved HFD-induced glucose intolerance and dyslipidemia by restoring the downregulated PPARγ in PA-induced HepG2 cells or HFD-fed mice." (PMID 30463189, 2018). "There is a strong consensus that the AROS axis (i) plays a central role in induction of the metabolic syndrome and (ii) is a target for the counteracting effects of PPARγ agonists." (PMID 28101123, 2017). "Analogously, formononetin and calycosin exhibited strong activation on PPARA and PPARG to correct dyslipidemia and to restore glycemic balance." (PMID 29051733, 2017). "In adipose tissue, expression of zinc influx transporter ZIP14 varies with body mass index (BMI), clinical markers of metabolic syndrome, and peroxisome proliferator-activated receptor gamma (PPARG)." (PMID 28303117, 2017). "A comprehensive systems biology approach was undertaken to examine the AROS axis during development of metabolic syndrome and the response to treatment with a PPARγ agonist (RGZ)." (PMID 28101123, 2017). "Our data demonstrate (i) the systems-level regulatory landscape of HFD-induced metabolic syndrome involving multiple molecular parameters, including HNE, AGEs and their receptor RAGE, and (ii) attenuation of metabolic syndrome by PPARγ modulation." (PMID 28101123, 2017). "More specifically, PPARα regulates lipid metabolism by targeting fatty acid and acyl-CoA and thus acts as protective factor in dyslipidemia, whereas PPARγ increases tissue insulin sensitivity and is a pharmaceutical target in diabetes mellitus." (PMID 27022389, 2016). "PPARγ agonists are insulin sensitizers, which improve glycemic control and reduce dyslipidemia, leading to antiatherogenic effects." (PMID 25785279, 2015). "The thiazolidinediones type PPARγ activators including troglitazone and pioglitazone improved the dyslipidemia by lowering the triglyceride levels in patients with dyslipidemia." (PMID 25861250, 2015). "Defects in PPARγ were reported to result in different pathological conditions in metabolic syndrome, including insulin resistance, obesity, dyslipidemia, and hypertension, and largely increase the risk of type 2 diabetes, cardiovascular diseases, and cancer." (PMID 26389882, 2015). "Here we investigate PPARG expression in different tissues and cells affected in metabolic syndrome and, in particular, during adipocyte differentiation of human mesenchymal stem cells." (PMID 24790595, 2014). "In this regard, capillary endothelial PPARγ can be a therapeutic target of dyslipidemia induced by a HFD." (PMID 23525438, 2013). "There are a number of studies demonstrating PPARγ as essential for AAMΦ activation and maturation in other disease states such as metabolic syndrome and leishmaniasis." (PMID 21772837, 2012). "PPARγ (C1431T and Pro12Ala) and RBP4 (−803GA) polymorphisms and metabolic syndrome among 91 HIV-infected patients." (PMID 23145084, 2012). "The influences of PPARγ (C1431T and Pro12Ala) and RBP4 (−803GA) polymorphisms on metabolic syndrome in HIV-infected patients receiving anti-retroviral therapy were examined in this study." (PMID 23145084, 2012).
metabolic syndrome (continued). "Synthetic drugs activating PPARα and PPARγ are in clinical use: the former typified by fibrates, are used to treat dyslipidemia, while the latter include glitazones that act as insulin sensitizers in type 2 diabetes mellitus." (PMID 21533120, 2011). "Synthetic PPARγ agonists (the glucose sensitizing thiazolidinedione (TZD) drugs) are potent drugs that improve insulin sensitivity in metabolic syndrome." (PMID 21382489, 2011). "Several glitazones (PPARγ agonists) and glitazars (dual PPARα/γ agonists) have been developed to treat hyperglycemia and, simultaneously, hyperglycemia and dyslipidemia, respectively." (PMID 21533120, 2011). "The present study demonstrated that rosiglitazone improved endothelial function in isolated arteries from a rat model of metabolic syndrome through both PPARγ- and PPARδ-mediated phosphorylation of Akt and eNOS." (PMID 22190906, 2011). "It is possible that PPARγ ameliorates metabolic syndrome solely by improving metabolic activities of target tissues involved in carbohydrate and lipid metabolism, as well as fat storage." (PMID 21382489, 2011). "Studies on ligand binding potential of glycyrrhizic acid, a potential agonist to PPARγ, displayed encouraging results in amelioration of metabolic syndrome." (PMID 20011054, 2010). "Agonists for both PPARγ and PPARγ have been used to treat dyslipidemia and hyperglycemia, respectively." (PMID 18769492, 2008). "PPARγ activation has beneficialeffects by lowering hyperglycemia and improving the metabolic profile inindividuals with type 2 diabetes and the metabolic syndrome." (PMID 18509499, 2008). "This can be explained by the fact that in the presence of severe dyslipidemia PPARγ activation in macrophages is insufficient to reverse the pro-atherogenic process." (PMID 18485218, 2008). "In contrast, drugs that target PPARγ appear, at least intheory, to offer an attractive and perhaps more logical approachto treating the metabolic syndrome, by virtue of their ability toameliorate insulin resistance and other facets of the condition." (PMID 17389771, 2007). "Downregulation by hypermethylation of PPARG in mouse adipocytes and fat tissues indicated a pathway for metabolic syndrome and may be altered in low birth weight human adults." (PMID 41246799, 2026). "Pan-NR agonists, such as RGX-202, activate PPARα, PPARγ, and PPARδ, leading to improvements in lipid metabolism, insulin sensitivity, and fatty acid oxidation, with potential applications for metabolic syndrome, dyslipidemia, and CVD." (PMID 40926269, 2025). "GDF10’s protective role against dyslipidemia and hypercholesterolemia may be attributed to its inhibitory effect on PPARγ as previously shown." (PMID 38245533, 2024). "Thus, it is evident that PPARγ is a critical regulatory target in osteoporosis triggered by dyslipidemia and lipid metabolism disorders." (PMID 38523674, 2024). "Therefore, regulating the activity of PPARγ can regulate lipid levels and thus osteoporosis due to dyslipidemia and disorders of lipid metabolism." (PMID 38523674, 2024). "Finally, PPARγ SUMOylation suppresses its transcriptional activity, thus inducing dyslipidemia and vascular SMC proliferation." (PMID 37570694, 2023). "Therefore, we found decreased expression of WNT5A in VAT (p = 0.034) and of PPARγ in SAT (p = 0.035) samples in patients presenting metabolic syndrome." (PMID 36077270, 2022). "Moreover, we reported PPARγ decreased expression in SAT (p = 0.020) of the patients who presented with dyslipidemia." (PMID 36077270, 2022). "PPARγ is an important target molecule for the inflammatory disease and metabolic syndrome." (PMID 33919837, 2021). "We previously showed that the specific PPARα agonist fenofibrate, an FDA-approved drug used to treat dyslipidemia with minimal activity toward PPARγ, upregulated PPARα target genes in the DRG and rescued the impaired axon growth in mice lacking fatty acid synthase in SGC." (PMID 34586065, 2021).